KLF4 (KLF transcription factor 4)
Diseases named in the same sentence as KLF4 in open-access papers (continued):
Sharing a sentence is not in itself a finding about the gene and the disease.
breast cancer (continued). "In breast cancer, ALKBH5 has been shown to promote tumourigenesis by decreasing adenosine methylation in KLF4 and NANOG mRNAs, enhancing their stability in breast cancer stem cells." (PMID 33461542, 2021). "We investigated the potential correlation between KLF4 expression and relapse-free survival (RFS) and overall survival (OS) rates of breast cancer patients using the Kaplan–Meier plotter database." (PMID 33918002, 2021). "We observed that the expression levels of both KLF4 and xCT in MCF-7, T47D and HS578T breast cancer cells were relatively high, while in BT549, MDA-MB-453 and NHFB breast cancer cells, they were relatively low." (PMID 34040532, 2021). "Here, we demonstrated that the KLF4 expression was correlated with PTX sensitivity and that breast cancer cells with a lower KLF4 level were less sensitive to PTX." (PMID 34150611, 2021). "Here, we demonstrated that DNMT1 promoted the methylation of KLF4 promoter and thus decreased KLF4 expression, which was correlated with the PTX sensitivity in breast cancer." (PMID 34150611, 2021). "At the same time, ATXN3 deubiquitinates and stabilizes KLF4, a closely related member of KLF5, enhancing cell migration and lung metastasis in breast cancer." (PMID 34575114, 2021). "As a transcriptional inhibitor of VEGF gene, Kruppel-like Factor 4 (KLF4) recruits HDAC2 and HDAC3 to the VEGF gene promoter for suppressing VEGF gene transcription in breast cancer." (PMID 34307380, 2021). "The results showed that the expression of DNMT1 was lower in breast normal tissues with relatively high KLF4 expression, while DNMT1 was significantly increased in breast cancer tissues with relatively low KLF4 expression." (PMID 34150611, 2021). "The expression of Krüppel-like factor 4 (KLF4) and DNA-methyltransferase 1 (DNMT1) in breast cancer tissues were assessed by immunohistochemistry and Western blotting." (PMID 34150611, 2021). "The results showed that KLF4 and SLC7A11 were positively correlated in basal-like breast cancer cells." (PMID 34040532, 2021). "In order to determine the mechanism governing the regulation of CSC by piR-823 in breast cancer cells, stem cell-regulating factors including OCT4, SOX2, KLF4, NANOG, and h-TERT were examined in MCF-7 cells after knockdown or overexpression of piR-823." (PMID 33791297, 2021). "Krüppel-like factor 4 (KLF4) is one of the most important transcription factors in eukaryotes and plays an important regulatory role in the occurrence and development of breast cancer." (PMID 34040532, 2021). "An in vitro and in vivo study performed by Zhou and colleagues showed that breast cancer cell metastasis is promoted by ATXN3 (Ataxin-3, ATX3, AT3 or MJD), which is a novel deubiquitinating enzyme of KLF4." (PMID 33266506, 2020). "The expression of KLF4 is significantly downregulated during EMT in mammary epithelial cells and in breast cancer cells." (PMID 33240028, 2020). "The expression of KLF4 and PARP1 is also significantly correlated with each other in these 117 cases of breast cancer tissues." (PMID 33231937, 2020). "In contrast to KLF4, KLF8 induces invasion, proliferation, and metastasis in breast cancer, and in human breast cancers, KLF8 and EGFR are co-elevated." (PMID 32552913, 2020). "In summary, the results from our preclinical model confirmed the potential clinical value for synergizing KLF4 and PARP1 in TNBC breast cancer therapy." (PMID 33231937, 2020). "Results of our preclinical study on synergism between KLF4 and PARP1 have shed light on a novel therapeutic strategy for the BRCA1‐proficient population of TNBC breast cancer patients." (PMID 33231937, 2020). "Although the function of KLF4 in breast cancer remains controversial, it is well established that KLF4 inhibits EMT in breast cancer cells." (PMID 33240028, 2020). "LINC01133 also regulates the pluripotency factor, Kruppel-Like Factor 4 (KLF4), which promotes stemness in breast cancer." (PMID 32244924, 2020).
breast cancer (continued). "Though KLF4 and EGFR are both widely studied in breast cancer, this is the first report linking their activities in this disease." (PMID 32552913, 2020). "The exosome-mediated transfer of miR-10b promotes cell invasion in breast cancer, suppressing the protein level of its target genes, such as HOXD10 (homeobox D10) and KLF4 (Krüppel-like factor 4)." (PMID 31752198, 2019). "DDX3X was notably found to reduce the expression of the cell cycle repressor KLF4, indicating the oncogenic role of DDX3X in breast cancer." (PMID 31906196, 2019). "Our findings show that both molecules increase epithelial to mesenchymal transition and migratory capacity of breast cancer cells, as well as cancer stem cell numbers, by increasing the expression of pluripotency genes such as ALDH1A1, KLF4, and NANOG." (PMID 30131941, 2018). "Here, we inserted the four stem cell transcription factor genes OCT4, SOX2, C-MYC and KLF4 into MCF cells (MCFs), represented a female breast cancer cell type, and obtained iPSCs (Mcfips) in about 3 weeks." (PMID 28423718, 2017). "The previous studies showed that Klf4 is essential for maintaining CSC-like cells in colon CSC-enriched spheroid cells and breast cancer stem cells, whereas Klf4-mediated suppression of CD44 signaling negatively modulated the stemness of pancreatic cancer." (PMID 29212199, 2017). "It was reported that EGR-1 can inhibit the growth of hepatocellular carcinoma cell lines and suppress the transformation activity in fibrosarcoma and breast carcinoma, ATF3 and KLF4 were reported as tumor suppressors in HCC." (PMID 29254483, 2017). "In the present study, hypoxia induced the HIF-dependent enrichment of BCSCs in all breast cancer cell lines, which was accompanied by increased expression of one or more pluripotency factors (NANOG, KLF4, or SOX2)." (PMID 27590511, 2016). "The regulation direction between KLF4 and S100A14 was also demonstrated in breast cancer, as was the inference from our Bayesian network." (PMID 27270322, 2016). "Forced increase of the KLF4α/KLF4(FL) ratio in the metastatic breast cancer cell line MDA-MB-231 decreases the levels of E-Cadherin, p21Cip1, and p27Kip1, three known KLF4(FL) target genes, and stimulates cell proliferation." (PMID 27323810, 2016). "In the present study, NFI-C was shown to regulate KLF4, a MET inducer, and subsequently controlled E-cadherin expression in normal mammary epithelial cells (MCF10A) and breast cancer cells (MCF7)." (PMID 25879941, 2015). "KLF4 is highly expressed in more than 70% of breast cancers and is especially enriched in cancer stem cell (CSC)-like cells from both mouse primary mammary tumors and in human breast cancer cell lines." (PMID 26517087, 2015). "Mutating KLF4 methylation sites suppresses breast tumour initiation and progression, and immunohistochemical stain shows increased levels of both KLF4 and PRMT5 in breast cancer tissues." (PMID 26420673, 2015). "Consistent with its regulation by miR-206 in breast cancer cells, CX43 was increased in KLF4-depleted MDA-MB-231 cells." (PMID 26053033, 2015). "It has been reported that the miR-10b can induce tumor invasion and initiate metastasis in breast cancer by targeting HOXD10 and promotes migration and invasion through direct binding with 3′-UTR of KLF4 in human esophageal cancer cells." (PMID 25428807, 2014). "Knockdown of KLF4 in the MCF-7 and MDA-MB-231 breast cancer cell lines drastically decreased the proportional number of CSC-like cells as defined by ALDH1 expression, side population and in vitro mammosphere formation capacity." (PMID 24429391, 2014). "Expression of key transcription factors Sox2, Oct4, Klf4 and c-Myc, were significantly up-regulated in the mammospheres isolated from SKBR3 breast cancer cells." (PMID 23341935, 2013).
breast cancer (continued). "This notion contrasts previous studies showing that Klf4 inhibits cell proliferation in a colon cancer cell line and that it acts as a pro-migratory factor in the MCF7 and MDA-MB-231 human breast cancer cell lines." (PMID 23451207, 2013). "KLF4 acts in concert with OCT4, SOX2, and NANOG in hESCs, but is downregulated in some breast cancer cells compared with normal mammary cells." (PMID 23596564, 2013). "Notably, mechanistic studies revealed the opposite effects of KLF4 on MDSC recruitment and immunosuppressive activity in breast cancer and GC." (PMID 41532367, 2026). "This is supported by an observation that the KLF4α isoform lacking the KLF4 exon 3 sequences antagonizes the function of full-length KLF4 in breast cancer and pancreatic cancer." (PMID 40552304, 2025). "Beyond the Wnt/β-catenin pathway, a well-established regulator of cancer stemness, we analyzed the expression of core pluripotency factors, including Nanog, KLF4, LGR5, and Sox2, which are critical for maintaining self-renewal, tumorigenicity, and therapy resistance in breast cancer stem cells." (PMID 41347072, 2025). "Ataxin-3 has been shown to deubiquitinate and therefore stabilise KLF4, and it is hypothesised that the up-regulation of ATXN3 observed in breast cancer contributes to up-regulation of KLF4, thereby accelerating breast cancer metastasis." (PMID 38497605, 2024). "Finally, in meta-analysis across multiple transcriptomic datasets belonging to breast cancer, ovarian cancer and bladder cancer, we investigated the correlation of ELF3, GRHL2 and KLF4 with epithelial and mesenchymal gene sets." (PMID 36864480, 2023). "In addition, ETS2 、ERαand Sp1, KLF4, and ZEB1/YAP have also been identified as regulators of hTERT transcription in breast cancer cells." (PMID 37612721, 2023). "EGR1 regulated KLF4 and vasculogenic expression in aggressive MDA-MB-231 breast cancer cells." (PMID 37762678, 2023). "MYC and KLF4 expression showed the most highly correlated expression profile (r = 0.35, p < 0.05) in the pan-cancer analysis while OCT4 and MYC expression was most positively correlated in the breast cancer analysis (r = 0.29, p < 0.05)." (PMID 37515162, 2023). "In the other words, enhancing SQLE expression increases Lnc030 levels which can boost the expression of some pluripotent transcription factors, such as c-Myc, Kruppel-like factor 4 (KLF4) and SOX2, which are helpful in maintaining breast cancer stem cells (BCSCs) stemness." (PMID 36230935, 2022). "DIM could enhance PTX sensitivity in MCF-7 and T47D breast cancer cells by reducing the expression of DNMT1 and subsequently reducing the methylation level of KLF4 and promoting the expression of KLF4." (PMID 34150611, 2021). "We observed that high KLF4 levels correlated with better relapse-free survival and better overall survival in two specific breast cancer datasets—GSE42568 (n = 104 breast cancer biopsies) and GSE3494 (n = 251 primary breast tumors)." (PMID 34680284, 2021). "Real-time PCR and Western blotting analysis revealed that DIM could significantly decrease the DNMT1 expression and increase the KLF4 expression in MCF-7 and T47D breast cancer cells." (PMID 34150611, 2021). "Factors other than AR may include KLF4 and c-MYC, which were found to be involved in breast cancer stem cell maintenance." (PMID 32781788, 2020). "Importantly, KLF4 is a key inducer of MET in normal mammary epithelial cells and breast cancer cells, through its ability to activate the epithelial program by triggering E-cadherin expression." (PMID 33266506, 2020). "Therefore, this study and our study showed that KLF4 represses DYRK2 gene expression in CML, while in breast cancer, DYRK2 prevents androgen receptor-mediated activation of the KLF4 gene." (PMID 33067577, 2020). "Additionally, there is a statistically significant positive correlation between KLF4 and PFKP expression in breast cancer tissues." (PMID 33266506, 2020).
breast cancer (continued). "Considering the homology ratio of KLF3 with KLF4 and KLF4 tumor-suppressor role, it can be assumed that KLF3 might also function to inhibit carcinogenicity in breast cancer." (PMID 33490232, 2020). "Surprisingly, the expression of KLF4 was significantly correlated with the expression of PARP1 and vice versa in breast cancer tissues, which indicates that KLF4 and PARP1 are co‐accumulated in most breast cancer tissue including TNBC, HER2‐positive, and ER/PR‐positive breast cancer." (PMID 33231937, 2020). "We examined the pattern of expression of KLF4 in seven different breast cancer cell lines as well as a non-transformed mammary epithelial cell line (MCF10A)." (PMID 32552913, 2020). "In breast cancer, DDX3X directly interacts with KLF4 mRNA and regulates its splicing." (PMID 31906196, 2019). "In breast cancer stem cells (BCSCs), ZNF217 has been reported to interact with METTL3 and inhibit the m6A methylation of KLF4 and NANOG, which ultimately leads to high expression of KLF4 and NANOG, thus promoting tumorigenesis." (PMID 30031372, 2018). "To understand potential links between aging and breast cancer stemness, we employed the GenAge Human Genes list to screen for genes that are correlated with core stemness factor OCT4, SOX2, NANOG, and KLF4 in a cohort of breast cancer cell lines collected from the TCGA database." (PMID 30038266, 2018). "Breast cancer stem cell (BCSC)-specific markers were highly reduced upon VDAC1 silencing in tumours established from the TNBC MDA-MB-231cell line, including ALDH1, CD133, EPCAM, SOX2 and KLF4." (PMID 30544833, 2018). "In accord with these results, breast cancer gene array profiling indicated that elevated expression of KLF4 in both MCF10A and MCF7 breast cancer cell lines upregulates transcription of several oncogenes and cell cycle activators such as MAPK, EGF/EGFR, IGF1, CYCLIN D2, CDK1, and CYCLIN E1." (PMID 30613353, 2018). "Taken together, our findings reveal a robust negative effect of DDX3X on the expression of KLF4 mRNA and protein and they suggest that DDX3X's biological function in MCF7 breast cancer cells is linked to its direct binding to KLF4 transcripts." (PMID 29782654, 2018). "To test the hypothesis, we first compared the expression of KLF4, ALDH1A1, ALDH1A3, CD44, and CD24 in human breast cancer samples available in TCGA database." (PMID 30038266, 2018). "Also, nuclear factor I-C overexpression induced the expression of Klf4 and E-cadherin and eventually suppressed EMT, cell migration, and the invasiveness of breast cancer cells." (PMID 28422735, 2017). "Breast cancer Met-1 cells were transducted with a DACH1 expression vector resulting in an ∼4.5-fold increase in DACH1 expression and subsequent reduction of CSC markers CD44, KLF4 and MYC as well as EMT markers including FN1 and VIM by mRNA analysis." (PMID 28659634, 2017). "Of note, KLF4 is also abundantly expressed and positively correlated with HBB levels in a cohort of 6 patient-derived breast CTC cultures, compared with a panel of 13 established breast cancer-derived cell lines (P=6.6E–04)." (PMID 28181495, 2017). "It was reported that Klf4 acts as a transcriptional activator of epithelial genes and as a repressor of mesenchymal genes to inhibit the EMT process, migration and invasion of breast cancer cells." (PMID 29212199, 2017). "To test whether normal and/or breast cancer cells express KLF4α, we used MCF10A and MDA-MB-231 cells and performed RT-PCR with primers flanking the KLF4 gene." (PMID 27323810, 2016). "Similarly, KLF4 inhibits epithelial-mesenchymal-transition (EMT) and metastasis in breast cancer models." (PMID 27323810, 2016). "It is well established that in breast cancer, miR-10b suppress migration and invasion property by directly targeting HOXD10 and RHOC.It has been known that miR-10b also interacts with KLF4 to stimulate migration and invasion potential in esophageal squamous cell carcinoma." (PMID 27467502, 2016).
breast cancer (continued). "We confirmed the ability of KLF4 to induce levels of E-Cadherin and p21Cip1 in the highly metastatic breast cancer cell line MDA-MB-231, but did not observe an increase of p27Kip1 upon forced KLF4 expression." (PMID 27323810, 2016). "KLF4 was similarly consistently elevated in lineage-negative (Lin-)/ALDHHigh MaCSCs isolated from human mammary tumor tissues that were passaged as PDXs." (PMID 26053033, 2015). "NFI-C overexpression induced expression of KLF4 and E-cadherin, but not Slug, in breast cancer cells." (PMID 25879941, 2015). "NFI-C, KLF4, and E-cadherin expression decreased in atypical ductal hyperplasia with breast cancer cells compared with atypical ductal hyperplasia without breast cancer cells." (PMID 25879941, 2015). "KLF4, an important inducer of MET, activates the epithelial program by triggering E-cadherin expression and induces MET in normal mammary epithelial cells and breast cancer cells." (PMID 25879941, 2015). "To address this, we examined whether NFI-C could regulate the transcription of KLF4 and E-cadherin and subsequently alter the expression of marker genes in MCF7 breast cancer cells." (PMID 25879941, 2015). "This is not surprising as it is well known that KLF4 acts as an oncogene during breast cancer progression." (PMID 25181544, 2014). "Our data support the hypothesis that KLF4 is a key regulator promoting MET and inhibiting EMT in ovarian and breast cancer cells." (PMID 25137052, 2014). "High expression of KLF4 (as defined by a Quick score of 9 or greater) was identified in 59% (44/75) of dogs with mammary carcinoma and none in the benign tumors." (PMID 21978458, 2011). "High KLF4 expression occurred only in the tumor cells and not the adjacent normal cells in mammary carcinoma (P < 0.001)." (PMID 21978458, 2011). "High KLF4 expression was identified in 44 of the 75 (59%) dogs with mammary carcinoma and none in the benign cases." (PMID 21978458, 2011). "Importantly, Elevated ANGPTL4 and KLF4 expression was observed in metastatic breast cancer specimens compared to non-metastatic cases and was positively correlated with poor prognosis." (PMID 40616161, 2025). "Notably, KLF4 plays a crucial role in maintaining CSC characteristics in liver and breast cancers." (PMID 40316546, 2025). "Furthermore, exposure of tbLCM or loss of function of DACH1 in breast cancer cells significantly increased expression of KLF4, CD44 and Vimentin, indicating that one or more secreted factors in the LCM derived from TNBC tumor-bearing mice influences stemness/plasticity in breast cancer cells." (PMID 38581619, 2024). "Furthermore, ZNF217, an m6A methyl-transferase inhibitor, inhibits the m6A modification of several pluripotency factor mRNAs, including NANOG, KLF4 and SOX2 in breast cancer to promote the CSC-like phenotype and breast cancer metastasis under hypoxic conditions." (PMID 34831207, 2021). "While previous studies have reported the use of microarrays to identify KLF4 gene targets in corneal, rectal carcinoma, and non-transformed mammary epithelial cell lines, no reports to date have examined the impact of KLF4 on the expressed proteome in breast cancer cells." (PMID 32552913, 2020). "Our findings that up‐regulation of KLF4 mRNA upon DDX3X knockdown in both MCF7 cells and MDA‐MB 231 cells suggests that the DDX3X:KLF4 axis of cell cycle regulation could be a common feature of breast cancer cell lines." (PMID 29782654, 2018). "Moreover, we discovered that KRT19 regulates CSC reprogramming and drug sensitivity in breast cancer and cancer stem cell-like cells, through mediating stemness (NANOG, OCT4, KLF4, and SOX2) and drug-resistant (ALDH1, ABCG2, ABCC1, and ABCB1) marker expression." (PMID 29747452, 2018). "Hence, KLF4α only had a growth-promoting effect on breast cancer cell lines, which was independent of their respective endogenous total KLF4 levels (low in T47D, high in MDA-MB-231)." (PMID 27323810, 2016).